PRL (prolactin)
Diseases named in the same sentence as PRL in open-access papers (continued):
Sharing a sentence is not in itself a finding about the gene and the disease.
tumor (continued). "Instead, the authors indicated that PRL may exert a modulatory effect on the neuronal excitability rather than tumour size." (PMID 36967387, 2023). "In addition, the patient responded to medical treatment with cabergoline, reducing prolactin and with normalization of testosterone and the patient's growth; moreover, the control MRI 3 months after treatment showed no increase in tumor size." (PMID 37908013, 2023). "Future studies are required to clarify if therapy with DAs might be continued after menopause considering the potential beneficial impact on cardiometabolic health, regardless of PRL and tumor status." (PMID 36237192, 2022). "The PRL secretion inhibition by BRC is mainly related to the stimulation of K+ and sodium (Na+)-ATPase activity and the increase of cytosolic Ca2+ concentration, which further inhibit cAMP production as demonstrated in rodent pituitary lactotroph normal and tumour cells." (PMID 35460460, 2022). "Therapies may be tapered or discontinued in patients who received a minimum of two years of DA and no longer have elevated serum prolactin levels and no visible tumor remnant on MRI." (PMID 36337795, 2022). "In patients with MP guidelines from ES suggested that Cab could be withdrawn if normal PRL levels are maintained for at least 2 years despite progressive lowering of Cab dose and no visible tumor remnant on MRI." (PMID 35000899, 2022). "The negative correlation between tumor volume and PRL may attribute to hypothalamic compression which disturbed the tonic release of dopamine." (PMID 35360427, 2022). "To investigate whether CASC15 exerts tumor-promoting effects in NSCLC cells by influencing the expression of neighbouring genes, we firstly performed qPCR to analyze the expression levels of SOX4 and PRL upon CASC15 silencing." (PMID 33407675, 2021). "Unfortunately, she experienced vision loss again, and MRI in March 2012 indicated a rapidly growing tumor with compression of the optic chiasm and invasion into the third ventricle, and the serum prolactin levels increased to 200.0 ng/mL (samples not diluted) again." (PMID 34715828, 2021). "Existing guidelines suggest that with careful clinical and biochemical follow-up, DA therapy may be tapered or discontinued after at least 2 years of treatment, if PRL concentration remains normal and there is no recurrent tumour on MRI5." (PMID 33963239, 2021). "A patient with a PRL secreting tumor treated with EVE 10mg + octreotide showed decreased PRL levels (454 ng/ml to 253 ng/ml; 55% reduction) after an initial 3 months of EVE therapy; however, PRL level gradually increased to its previous level by 5 months following initiation of EVE therapy." (PMID 33841328, 2021). "This lower molecular weight isoform product of native PRL impairs functional tumor neovascularization by altering Notch signaling, particularly due to its inhibitory effect on vessel maturation through its binding to fibrinolytic inhibitor plasminogen activator inhibitor-1 (PAI-1)." (PMID 34745013, 2021). "Since the PRLR/PRL axis has been implicated in other tissues, including reproductive tissues and prostate, h16f-MMAE and ABBV-176 conjugates were evaluated for their ability to inhibit the growth of non-breast-derived tumor cell lines." (PMID 34107902, 2021). "According to the multivariate analysis, only tumor located in the right-hemicolon, elevated CEA level, extended PM, CCR0/1 and high SII value were independent factors associated with a worse prognosis, rather than NRL value and PRL value." (PMID 32742472, 2020). "Guidelines suggest that withdrawal of DA may be attempted after at least two years of therapy if PRL has normalized and there is no visible tumour on MRI; remission rates of 26 to 69% have been observed following discontinuation." (PMID 31847209, 2019).
tumor (continued). "In a small number of patients in the clinical setting, the preferred CAB treatment does not normalize serum PRL levels and may fail to shrink the tumour by >50%, even at very high doses; these patients may respond to BRC13." (PMID 31000722, 2019). "In most of PRL-omas, treatment with DAs, normalization of prolactin and tumor shrinkage could be achieved and do not require other surgical or radiotherapy interventions." (PMID 31191457, 2019). "Both the level of PRL and the tumor size were gradually reduced without further seizures." (PMID 30660191, 2019). "Regarding cabergoline, resistance has been arbitrarily defined when there is no normalization of prolactin concentration and a reduction in tumor size of <50% at the maximum dose of 2.0 mg per week for 3 months, which is the dose recommended by the manufacturer as the most effective." (PMID 30542321, 2018). "Patients who did not achieve normalized prolactin blood concentrations and a reduction of more than 50% of the tumor volume with the minimum dose of 3.5 mg per week of cabergoline for 3 months or the maximum supported dose of bromocriptine for 6 months were considered resistant to dopamine agonists." (PMID 30542321, 2018). "In some cases, treatment of prolactinomas may normalize prolactin concentrations without altering tumor volume or, in rare circumstances, may decrease tumor volume without normalizing prolactin concentrations." (PMID 30542321, 2018). "The tumour expressed the GH gene at high levels (more than 3 FC) without gene expression of PRL." (PMID 28692683, 2017). "It is not frequently observed that a tumor becomes bigger without increasing PRL levels." (PMID 26909481, 2016). "However, the exact mechanisms guiding PRL-induced cell migration and tumor metastasis are not fully understood." (PMID 27542844, 2016). "Recently, several investigations identified that serum PRL levels were significant elevated in HCC patients and PRL was one of the potential tumor markers for HCC, suggesting that hPRL may be useful as a biomarker for early detection of HCC and may play a role in HCC progression." (PMID 27102295, 2016). "At present, it is still not clear whether PRL acts as a promoter or a suppressor of neoplasm development or as a promoter of differentiation." (PMID 26370564, 2015). "Thus, pituitary surgery for macroprolactinomas usually results in significant tumor debulking, but without PRL normalization." (PMID 28702224, 2015). "In conclusion, a second attempt of CAB withdrawal after two additional years of therapy may be successful, particularly in patients with lower PRL levels and no visible tumor on pituitary MRI." (PMID 25699020, 2015). "On the other hand, survivin was not correlated with prolactin levels and tumor size." (PMID 25699121, 2015). "PTTG did not correlate with prolactin levels or tumor size in animal models of prolactinoma, and its pituitary content was not related to a decrease in dopaminergic control of the lactotrope, but it was positively influenced by estrogen action at the pituitary level." (PMID 25505910, 2014). "While a component of the anti-tumor effects were hypothesized to result from indirect activity toward prolactin production as well as neural-immune responses, direct effects of L-deprenyl on tumor cells were not ruled out." (PMID 25198178, 2014). "Conversely, her prolactin level remained abnormal at 28.0 (one month post-operatively) and 29.3 (3 months post-operatively) and 42.6 ng/ml (6 months post-operatively) (NV<23.3), showing that the prolactin-secreting tumor was not completely resected." (PMID 25298881, 2014). "Consistent with local acidosis-mediated suppression of prolactin signaling, GLUT1-positive regions as well as the immediately surrounding zone lacked prolactin-inducible pYStat5 response whereas regions of GLUT1-negative tumor cells displayed robust pYStat5 signal." (PMID 24004716, 2013).
tumor (continued). "The addition of a non-parathyroid, prolactin-responsive control as a comparison could make an interesting backdrop to a future delineation of the PRLr receptor in human tumour systems." (PMID 22606260, 2012). "Resistance to dopamine agonists can be defined as a failure to achieve normalization of prolactin levels or no reduction in tumor size after 12-24 months of bromocriptine 15 mg/day or cabergoline 0.5 mg/day; most cases of resistance to dopamine agonists can be considered partial resistance." (PMID 20478050, 2010). "However, in no case of biochemical recurrence did the tumor regrow or symptoms reappear; therapy was reinitiated when prolactin rose." (PMID 20478050, 2010). "There are studies that support the tumour marker value of PRL and studies that do not." (PMID 15617576, 2004). "In addition, the in vitro experiments evaluated PRL secretion, but did not include assessment of cell growth markers, which may have provided data on the potential anti-tumor effects of pasireotide." (PMID 41184667, 2025). "However, prolactin levels at diagnosis did not significantly differ between the two groups (801 vs. 1220 μg/L in the surgical and medical groups, respectively; p = 0.374), suggesting similar tumor burden." (PMID 40035956, 2025). "Similarly, macrophages in metastatic UVM showed strong enrichment for cytokines like Adiponectin, Prolactin, IL7, IL10, IL15, IL9, IL31, APRIL, Persephin, and IL22, highlighting their role in creating a pro-tumorigenic environment through immune modulation and support of tumor growth." (PMID 39916959, 2024). "However, no noticeable effect was observed in terms of tumor progression or serum prolactin levels." (PMID 37529607, 2023). "Indeed, pituitary IL-6 may provoke contrary effects (inhibitory or stimulatory) in different tumours such as ACTH-, PRL-, GH-secreting and non-functioning tumours." (PMID 35837315, 2022). "However, whether this was a direct effect of prolactin on tumor parenchyma or through stromal cells, or both, was not determined." (PMID 34375938, 2021). "However, conservative treatment with prolonged use of cabergoline, combined with mirtazapine and quetiapine, may have contributed to cystic degeneration of the tumor, despite the fact that our patient’s prolactin levels never normalized." (PMID 31202268, 2019). "It has been proposed that the detection of PRL by immunohistochemistry in GBM specimens but not by real-time PCR indicates that the presence of PRL in primary tumours may not be a reflection of local production, but rather of circulating PRL that access the tumour." (PMID 31862900, 2019). "For this reason, this study focused on analyzing the contribution of 17β-estradiol (E2), PRL, and HPV on the expression and localization of hormone receptors, as well as to evaluate whether these hormones may promote greater expression of HPV oncogenes and contribute to tumor progression." (PMID 31507337, 2019). "Thus, the capacity of PRL/STAT5 signaling to induce the amplification of stem/progenitor cells may directly contribute to cancer progression by feeding the prostate tissue with cells able to resist treatments and to regrow a tumor (cancer recurrence)." (PMID 31269779, 2019). "Radiotherapy may be useful to control tumor growth but not for normalizing prolactin concentration." (PMID 30542321, 2018). "We conclude that PTTG does not correlate with prolactin levels or tumor size in animal models of prolactinoma, and its pituitary content is not related to a decrease in dopaminergic control of the lactotrope, but may be influenced by estrogen action at the pituitary level." (PMID 17222350, 2007). "Pathological examination confirmed double PitNETs comprising a GH/TSH secreting mature plurihormonal PIT1-lineage tumor (GH++, TSH±, PRL-, PIT1+) and a non-functioning gonadotroph tumor (FSH+, SF1+)." (PMID 40002269, 2025).
tumor (continued). "Most patients with prolactinoma are expected to show a reduction in tumor size with a substantial reduction in prolactin levels; moreover, in most cases, a patient who has minimal or no PRL reduction will also have no reduction in tumor size." (PMID 36835974, 2023). "However, we found that when cystic pituitary prolactin-secreting macroadenomas were reduced to a certain extent, even if the maximum safe dose of bromocriptine treatment was maintained, the tumor did not continue to shrink, and the PRL levels of the patients could not be reduced to a normal level." (PMID 35741585, 2022). "Some exceptional plurihormonal tumours from different lineages were also observed; two ACTH/LH ± α-subunit glycoprotein, two ACTH/GH ± PRL, one TSH/FSH/LH (SF-1, but not Pit-1 positive)." (PMID 36018781, 2022). "Conversely, TGFB2 expression was significantly higher in GH-secreting (4.2-fold, p<0.0001) and PRL-secreting tumor tissue (6.1-fold, p<0.0001), but not in NFA and ACTH-secreting tumor tissue, than in normal pituitary tissue." (PMID 35600354, 2022). "Regardless of tumor size, IGF-I evaluation should be performed at diagnosis in all patients with prolactinomas to rule out a mixed hypersecretion of GH and PRL." (PMID 35000899, 2022). "In seven patients with carcinomas (five ACTH positive, one PRL positive, and one PIT-1 positive), five patients (71%) initially showed partial reduction of tumor size in response to CAPTEM treatment and no tumor progression for as long as 39 months." (PMID 33841328, 2021). "In the present study, DRD2 knockout mice were selected as the model, and inhibition of MAPK14 reduced the secretion of PRL and growth of tumor, suggesting that DRD2 activation is not the only means of regulation of expression of PRL." (PMID 32894113, 2020). "PRL expression was also detected in human GBM xenografts, which was notorious in tumour cells infiltrating the non-neoplastic brain tissue." (PMID 31862900, 2019). "It is noteworthy that the inhibitory action of retinoic acid seems to be restricted to ACTH-secreting tumor cells, since, in rat normal pituitary cells, neither ACTH, prolactin, nor growth hormone is affected by the treatment." (PMID 27034666, 2016). "In this case, the tumor cells were proven chromophobic by Pearse’s PAS stain, showing immunopositivity for PRL, chromogranin-A, and synaptophysin but no immunoreactivity to S-100 protein, vimentin, and GFAP." (PMID 26228535, 2015). "All patients presented with normal PRL levels, were given CAB doses (1 mg weekly, and had either no visible tumors or small tumor remnants (<1 cm) on MRI." (PMID 25699020, 2015). "Hence, we propose that chronic lack of physiological proapoptotic and antiproliferative actions of PRL, and/or changes in PRLR expression, could contribute to alterations in anterior pituitary cell renewal, leading to pituitary hyperplasia and, eventually, tumor development." (PMID 24859278, 2014). "The absence of GH and prolactin staining on the second post-operative specimen could reflect either selection of a particular clone of cells over time or pretreatment with octreotide whose morphological effects are still not fully understood rather than sampling of a different area of the tumour." (PMID 24616766, 2013). "We found that phospho-Ser536-p65 expression was positively related to TEM1, FXYD-3, PRL, p73 and MAC30 in tumours that received RT, however there were no such relationships in the non-RT group." (PMID 22933966, 2011). "The tumor cells were negative for epithelial membrane antigen, synaptophysin, periodic acid-Schiff (PAS), and pituitary hormones (adrenocorticotropic hormone, human growth hormone, and prolactin)." (PMID 31689841, 2019). "However, unlike the evaluation of prolactin in BIPSS, the role of prolactin evaluation in improving tumor location is still in its infancy, and further studies are thus needed to support its use." (PMID 27355856, 2016).
tumor (continued). "Importantly, in the PRL treated group no FDG uptake was observed except for brain, heart, and bladder suggesting absence of tumor formation in this group of mice." (PMID 27480353, 2016). "Additionally, as with PRL and PRLR, the base RNA levels of IGF1 were 3-fold lower than GH levels and the modulated-GH-action induced changes in IGF axis apparently had no observable variation on intracellular signaling or tumor phenotypes." (PMID 28223541, 2017).
cancer (289 papers, 1986 to 2026). A tumor composed of atypical neoplastic, often pleomorphic cells that invade other tissues. "Our findings refine our understanding of PRL catalysis and identify novel mutations for investigating PRL function in cancer and magnesium homeostasis." (PMID 40398601, 2025). "Changes in intracellular magnesium, linked to cancer progression, result from the formation of a PRL-CNNM complex." (PMID 39691602, 2024). "Other studies have observed an increase in cardiovascular and all-cause mortality in men and women, and cancer death in men, with higher levels of PRL." (PMID 38829475, 2024). "Due to their cell proliferative property, PRL has been implicated in the initiation and progression of cancers; antagonizing PRLR in certain tumors has therefore shown anti-proliferative effects on their cells." (PMID 35406699, 2022). "The ability of PRL to expand these epithelial subpopulations would contribute to increased cancer risk." (PMID 35784527, 2022). "Target genes of the top 10 miRNAs were associated with cancer, prolactin pathway, EGFR, ErbB, and FoxO signaling pathway." (PMID 36313069, 2022). "Several publications suggest that activation of the PRL/PRLR signaling pathways is linked to cancer via activation of JAK/STAT, PI3K, AKT and MAPK pathways." (PMID 34358244, 2021). "In this study we performed RNA-sequencing of MCF7 cells expressing single-point phospho-deficient STAT5a mutants treated with PRL in attempts to identify differentially expressed genes and functional pathways for cancer outgrowth." (PMID 34188118, 2021). "Early studies with the PRLR antagonist hPRL-G129R – a variant of normal human prolactin with a single amino acid substitution mutation – revealed its capacity to inhibit the prolactin-induced oncogenic signaling responsible for cancer cell proliferation." (PMID 33335078, 2020). "Several publications suggest that activation of the PRL/PRLR signaling pathways is linked to cancer via activation of PI3K, AKT, and MAPK pathways, which are important in tumorigenesis." (PMID 32121009, 2020). "An association with PRL levels and breast, ovarian, colon and hepatocellular cancer has been suggested." (PMID 31847209, 2019). "Although basic science studies have implicated a role for PRL and its receptor in the pathogenesis of different malignancies, a clear causal relationship between PRL and cancer remains controversial." (PMID 31847209, 2019). "The associations of PRL and development of various cancer has been evaluated in breast, prostate, colorectal, gynecological, and hepatocellular cancer." (PMID 30555348, 2018). "Recent large epidemiologic studies have correlated elevated exposure to PRL with increased risk for development of aggressive ERα+ cancers." (PMID 27344177, 2016). "They found PRL tissue levels to be significantly associated with the malignancy of tumors, with malignant tumors expressing the highest levels." (PMID 22647582, 2012). "Progress in the field of pharmacogenomics has led to increasing concerns about the complex relationships among serotonin, SSRIs, certain TCAs, prolactin, and tamoxifen, and how these inter-relationships affect pharmacodynamics and cancer risk." (PMID 21494667, 2011). "Elevated serum prolactin is associated with increased risks of cancers." (PMID 39201626, 2024). "The top 10 most abundant miRNAs identified in bEVs are associated with cancers and prolactin signaling pathways, which might be related to mammary epithelial cells." (PMID 36313069, 2022). "Several aspects regarding this hormone ́s roles in the endometrium have been studied, such as its expression, the activation of cancer-associated signaling pathways, and its biological effect on decidualization, making PRL a relevant factor in the carcinogenesis and progression of EC." (PMID 34745013, 2021). "Many studies have linked prolactin levels with the development of various forms of cancer." (PMID 29379595, 2017).